C8orf90 (chromosome 8 open reading frame 90)
Gene: Protein-coding gene on chromosome 8 (141,514,638 to 141,518,737, forward strand). Ensembl gene ENSG00000226490.
Homologues: Orthologues: macaque C8orf90 (96% identical), chimpanzee C8orf90 (95% identical), mouse Gm6569 (69% identical), rat Gm6569 (65% identical), guinea pig C8orf90 (64% identical).